CD86 (CD86 molecule)
Diseases named in the same sentence as CD86 in open-access papers (continued):
Sharing a sentence is not in itself a finding about the gene and the disease.
tumor (continued). "Local irradiation with a single dose of 9 Gy increased expression of CD40 and CD86 on CD103+ DCs, suggesting maturation of Flt3L-induced tumor-residing CD103+ DCs." (PMID 33110069, 2020). "The activation status of DCs, assessed as upregulation of CD86, CD80 and CD40 when co-cultured with virus-infected tumor cells, was both virus and cell line-dependent, with some degree of activation in all cases." (PMID 31969562, 2020). "Results demonstrated that high CD86+ and low CD206+ TAMs infiltration were significantly correlated with certain favorable tumor clinicopathologic features and better prognosis in ICC patients, when compared to low CD86+ and high CD206+ TAMs infiltration." (PMID 32002338, 2020). "Other negative regulators, as already discussed, are the immune checkpoints expressed by tumor cells and myeloid-derived cells, such as PD-L1 and CD80/CD86, respectively, which interact with PD-1 and CTLA-4 expressed on the T cell surface." (PMID 35582441, 2020). "Our data also showed that YPF decreased the levels of TSLP, TSLPR, and OX40L, increased the expression of CD80, CD86, and MHC-II in DCs, and stimulated the maturation of DCs in tumor and adjacent tissues of mice bearing with HCC." (PMID 32351590, 2020). "The 48 h coculture initiates a pro-tumor phenotype skewing of MΦ, indicated by downregulation of IL1B, IL12, CCL18, CD80, as well as CD163, and upregulation of CLEC7A (dectin-1), CD86, CD206, and HLA-DR." (PMID 30850595, 2019). "For infiltrating TAMs, after adjustment for tumor purity, in LIHC, FUNDC1 was positively correlated with CD80 and CD86, and in LUSC, FUNDC1 negatively correlated with CD80, indicating the constitutive effect of TAMs on differences in tumor cell survival." (PMID 31998650, 2019). "DCs play key roles in the tumor-antigen presentation and the priming of effector T cells, and CD80 and CD86 are two markers of DC maturation and are critical for the activation of costimulatory signaling during DC priming of CD8+ T cells." (PMID 31771653, 2019). "On day 14 after treatment, cryo-thermal therapy markedly induced high expression of CD86 and MHC II (on day 26 after tumor inoculation)." (PMID 30833570, 2019). "We selected the OPM-2 as the MM target in vivo since this tumor cell line lacks the expression of co-stimulatory molecules, while the other tumor cell lines retain the expression of either CD80 or CD86." (PMID 31040928, 2019). "We have previously shown that single agent B10G5 enhances DC activation in tumor draining lymph nodes and increases the expression of DC co-stimulatory molecule CD80 and CD86." (PMID 31446896, 2019). "Matured DCs (≥ 60% upregulation of CD80, CD86, CD83, and CCR7) produced high levels of the Th1 effector cytokine, IL12-p70 (1.2 ng/ml; p < 0.0001), compared to DCs pulsed with tumour lysate, or matured with an interferon-containing cocktail alone." (PMID 30283982, 2019). "Tumor-derived TGF-β suppresses CD80 and CD86 costimulatory molecule expression by DCs and promotes the development of a PD-L1-expressing immunosuppressive DC subset capable of inhibiting CD8+ T cell activity in a metastatic ovarian cancer model." (PMID 31921140, 2019). "We found that BMDCs cultured with tumor‐conditioned serum had lower MHC‐II, CD86, and CCR7 expression accompanied by higher levels of PD‐L1 compared with the control group." (PMID 30628173, 2019). "mDCs able to present tumor antigens to T cells were confirmed by the presence of surface markers CD80, CD83, and CD86 and HLA-ABC and HLA-DR antigens." (PMID 31546936, 2019). "Butyric acid enhanced granulocytic maturation of AML cells, and just like other HDACi, induced expression of costimulatory and adhesion molecules (CD80, CD86, HLA-DR, HLA-ABC, and ICAM-1) in AML cells, inducing anti-tumor immune responses." (PMID 31739588, 2019). "Consistent with the tumor being immune suppressed, both CD103+ DCs and CD11b+ DCs in non-treated tumors expressed relatively low levels of the activation marker CD86." (PMID 31036082, 2019).
tumor (continued). "Tumors with high T-cell signatures from our clustering analysis are concordant with high expression of PD-L1, PD-L2, PD-1, CD80, CD86, CTLA-4, Tim-3, LAG3, 4-1BB, CD8, and CD4, EBV-positive status, and low tumor purity and high immune score." (PMID 30911684, 2019). "These iron-positive macrophages (iTAMs) are hallmarked by low expression of the iron exporter ferroportin and positivity for CD86, CD163, and HMOX1 as well as a pro-inflammatory phenotype with the ability to kill tumor cells." (PMID 31383898, 2019). "We observed that CD103 + dendritic cells had indeed upregulated CD86 and CCR7 within the tumor after 12 h, and observed a corresponding increase in activation and accumulation within the draining lymph node at 48 h." (PMID 30718505, 2019). "The administration of Poly I:C matured tumour-infiltrating DCs that were initially in a more immature state and expressed less CD40, CD86 and MHCII, hence eliciting a greater anti-tumour activity." (PMID 31091774, 2019). "For this purpose, we challenged them with whole tumor cell antigens or with TNF-α plus LPS and compared the expression of HLA-DR and CD86." (PMID 29434528, 2018). "Recently, it has been suggested that tumor-infiltrated B cells develop immunosuppressive properties via enhanced expression of TGF-β, PD-L1, CD86, and IL-10." (PMID 29599908, 2018). "Tα1-Fc displayed a more effective antitumor activity in the 4T1 and B16F10 tumor xenograft models by upregulating CD86 expression, secreting IFN-γ and IL-2, and increasing the number of tumor-infiltrating CD4+ T and CD8+ T cells." (PMID 30120362, 2018). "In contrast with the hypothesis of protective role of higher CD80/CD86 gene expression, we also found that upregulated expression of CD86 associated with a greater tumor size (pT3-4) and that nonmetastatic PTC (pN0) had a reduced expression of CD80 compared to metastatic ones (pN1)." (PMID 30123257, 2018). "In the lung, CpG administration induced the upregulation of CD86 by both CD11b+ and CD103+ conventional DCs (cDCs) subsets in tumor-bearing mice." (PMID 29844317, 2018). "The expression levels of CD80, CD86, and CD69 in B220+ B cells from splenocytes of HHT-treated mice were higher than that of control mice in two mouse tumor models." (PMID 29844447, 2018). "The tumor-bearing mice treated with HHT and NAR exhibited increased CD80 and CD86 expression in B220+ B cells of splenocytes as compared to untreated mice." (PMID 29844447, 2018). "Dendritic cells isolated from the brains of tumor bearing animals were assessed for expression of known activation markers, including CD80 (B7-1), CD86 (B7-2), and I-Ab major histocompatibility complex (MHC) class II." (PMID 30211113, 2018). "Conventional and monocyte-derived dendritic cells in the tumor-draining lymph nodes (dLN) of C57BL/6 and PLT2 mice were similarly increased after Poly I:C immunotherapy, and expressed high levels of CD40 and CD86." (PMID 30383838, 2018). "Although M1 macrophages has anti-tumor function, our data shows markers including CD68, CD86, TLR2 and TLR4 are correlated with CD163 too." (PMID 29152078, 2017). "Then, tumor DNA escapes to the cytoplasm of DCs and activates the cGAS–STING pathway, inducing the production of type I IFN and the co-stimulatory molecule CD86, and activating a Th1 response." (PMID 29050360, 2017). "Common up-regulated genes are related to transcription regulation (HMBOX1, LINC00340, NEXN-AS1), immune response (CD86, IL6, IFIT2) and the last two are potential tumor suppressors (LRRC2 and SPINK6)." (PMID 28035074, 2017). "While DCs did migrate in vitro similarly toward SN of mock treated and irradiated tumor cells, in particular SN of irradiated tumor cells induced an increased expression of the activation markers CD80 and CD86 on DCs." (PMID 28337197, 2017).
tumor (continued). "In different tumor mouse models, T cells expanded from OKT3-28BB/CD86/4-1BBL RNA electroporation showed anti-tumor activities superior to those of OKT3/IL-2 T cells and similar to those of CD3/CD28 Dynabead T cells." (PMID 28523432, 2017). "Across both genotypes, tumour-resident CD103+ DCs expressed 1.5–3-fold higher levels of both co-stimulatory (CD80/B7-1, CD86/B7-2) and –inhibitory (PD-L1/B7-H1, PD-L2/B7-DC) surface molecules as compared to CD103− DCs." (PMID 28924177, 2017). "Amongst other parameters, DC maturation is also inhibited by the tumor microenvironment, which is characterized by a reduced expression of CD83 and CD86." (PMID 28719632, 2017). "Confocal analysis of tumor sections, double stained with anti-CD206 or anti-CD86 and anti-v-ATPases, revealed that both tumor cells and TAM expressed v-ATPases, the fluorescence intensity being much higher in macrophages." (PMID 28978047, 2017). "As a receptor expressed on CD4+, CD8+, and regulatory T-cells, CTLA-4 competitively disrupts the axis between tumour-specific T-lymphocytes bearing CD28 receptors and stimulatory ligands CD80 (B7) and CD86 (B70) on antigen-presenting cells." (PMID 28571578, 2017). "In tumor tissues, the number of CD68 positive cells (median, 67 cells/field) was higher than CD86 positive (median, 37 cells/field, p < 0.001) and CD206 positive cells (median, 33 cells/field, p < 0.001)." (PMID 26938527, 2016). "Low presence of CD86+ and high presence of CD206+ TAMs were clearly correlated with aggressive tumor phenotypes, such as multiple tumor number and advanced TNM stage; and were associated with a poor prognosis in survival and recurrence." (PMID 26938527, 2016). "Uracil auxotrophs stimulate high-level expression of co-stimulatory molecules CD80 and CD86 as well as IL-12, and tumor antigen specific CD8+ T cell populations that mediate the long-term survival of tumor-bearing mice." (PMID 27447180, 2016). "Some DCs displayed mature phenotypes in the tumor tissues of CTX-ACT-treated mice and presented high MHC-II and CD86 expression." (PMID 27855783, 2016). "As compared to conventional DC-tumor FCs, we have previously demonstrated that fusions generated with DCs and heat- or ethanol-treated tumor cells upregulate multiple HSPs, MHC class I molecules, MHC class II molecules, TAAs, CD80, CD86, and IL-12." (PMID 27240347, 2016). "All CD40+, CD80+, CD86+ and MHC-II+ of DCs were significantly up-regulated upon the cGAMP treatment in tumor-bearing mice." (PMID 26754564, 2016). "MDSCs obtained from tumors and spleens of tumor bearing mice treated with IL-12 up-regulated the surface markers of macrophages (F4/80 and MHC II) and DCs (CD80 and CD86) suggesting differentiation into more mature, less immunosuppressive forms." (PMID 27246354, 2016). "The spleens obtained from tumor-bearing mice also had up-regulation of many dendritic cell and macrophage maturation markers such as CD80, CD86, F4/80 and MHCII." (PMID 27246354, 2016). "On the other hand, there was a trend that the percentages of F4/80 expression and F4/80, CD86 and MHC II co-expression on MDSCs in the cryo-thermal group were higher compared to the tumor-bearing control group." (PMID 27256519, 2016). "Our findings show that tasquinimod changes the polarization of macrophages in the tumor by several different parameters, such as an increase in MHC class II, CD86 and Nos2 expression and a reduced arginase-1 and CD206 expression." (PMID 26673090, 2015). "As expected, expression of HLA-DR and CD86, which are well known as markers of M1 macrophages, were up-regulated on CD14+ monocytes within PBMC co-cultured with tumor cells in the presence of cetuximab (p = 0.004)." (PMID 26579227, 2015). "The mRNA levels of CD86 and ICAM-1 in tumor tissues collected at 14th day after HIFU treatment were significantly increased in the HIFU group." (PMID 26485753, 2015).
tumor (continued). "As markers of such an immune response we analyzed shrinkage of tumor spheroids, CD80/CD86 expression on antigen-presenting cells (APCs), and granzyme B (GrB) expression by CTLs." (PMID 25871398, 2015). "In summary, our results demonstrate that HIFU down-regulates miR-134 to increase CD86 expression, which promotes T cell activation that, in turn, potentiates HIFU's anti-tumor effects." (PMID 26485753, 2015). "In tumor, inhibition of PD-1 effectively augmented CD40+, CD80+, CD86+ cells, and especially significantly increased MHC-II+ DCs." (PMID 26573233, 2015). "It was shown that after 7 days of differentiation with HCC tumour supernatant (TSN), the TSN-derived TAMs exhibited high expression of CD206 with relatively low CD86; indicating TAMs are prone to M2-like phenotype." (PMID 26492375, 2015). "Here, we show that tasquinimod treatment induces an anti-tumor effect which is subsequent to a reduction in tumor infiltrating CD206+ M2 macrophages and a simultaneous increase in M1 macrophages expressing MHC class II and CD86." (PMID 26673090, 2015). "In tumor bearing Tgfbr1/Pten 2cKO mice, PD-1 blockade increased MHC-II+, CD40+, CD86+ cells in spleen." (PMID 26573233, 2015). "CD14+ naïve monocytes from the co-cultures of tumor cells, cetuximab and HNSCC patient PBMC or purified monocytes were skewed to an M1-like phenotype, with increased expression of HLA-DR, CD86 and production of IL-12 p70." (PMID 26579227, 2015). "These induced DAMPs played an important part in activating DCs by PDT-treated tumor cells, including phenotypic maturation (increase of surface expression of MHC-II, CD80, and CD86) and functional maturation (enhanced capability to secrete IFN-γ and IL-12)." (PMID 26625309, 2015). "Flow cytometric analysis of the harvested tumor lysate-loaded DCs revealed a phenotype characteristic of mature DCs with high expression of CD40, CD80, CD83, CD86, HLA-ABC, HLA-DR, and CCR7." (PMID 25694811, 2014). "Tumor samples revealed a higher percentage of activated B cells (characterized by expression of CD19, CD20 and CD86) than PBMCs of CRC patients (16.8% vs. 4.1%, p <0, 005) or healthy controls (16, 8% vs. 4, 5%, p<0, 005)." (PMID 25026291, 2014). "Forty-eight hours later, mice were euthanized and the maturation status of DC within the spleen and tumor-draining lymph nodes (TDLN) was assessed using flow cytometry by costaining for CD11c and the maturation markers CD80, CD86, I-A/I-E, and CD40." (PMID 23935927, 2013). "The expression of CD86 is both necessary for and correlated to the efficacy of MHC class I restricted activation of anti-tumor CD8+ T cells by APCs." (PMID 26824927, 2013). "Next, to assess the phenotypic characterization of DC/tumor, the mean fluorescence intensity (MFI) of HLA-DR and CD86 expression by DC/tumor were determined by FACS analysis, where the fused cells were identified as MUC1+HLA-DR+ or MUC1+CD86+." (PMID 23555011, 2013). "Exposure of primary CLL cells to lenalidomide in vitro leads to the induction of costimulatory molecules like CD80, CD86, and FASL on the tumor cells, restoring immunological synapse formation and improving autologous tumor cell recognition by T cells." (PMID 22888354, 2012). "One approach is to include lymphokines (GM-CSF, IL-12, IL-15) or include tumour cell expression of membrane bound molecules (CD80, CD86)." (PMID 23046944, 2012). "These tumor cells were positive to the surface markers CD19, B220, CD5 and IgM, and also expressed the co-stimulatory molecules CD80, CD86 as well as CD117." (PMID 21269511, 2011). "Treatment with CT extract maintained the high profile of cell surface markers, such as CD80, CD86, MHC-I and MHC-II on the CD117+-derived CDs in the presence of tumor antigen." (PMID 19001481, 2011). "Among them, proteins of the B7 family play important roles in the immunoevasion of tumor cells and can suppress T-cell-mediated immunity by binding to the inhibitory receptor CTLA-4, e.g. B7.1 (or CD80) and B7.2 (or CD86)." (PMID 21884581, 2011).
tumor (continued). "DCs were evaluated for antigen uptake, and following maturation with LPS and IFN-gamma, DCs were assessed for expression of CD80, CD40, CD86, ICAM-1 and CCR7, production of IL-12p70 and IP-10, and induction of tumor-specific T-cell responses." (PMID 22194898, 2011). "Significant surface expression of CD86 and CD80 and MHC-II molecules was noted in DCs 48 hours post-electroporation with tumor cell RNA in the presence of TNF-α and LPS." (PMID 18445282, 2008). "In this perspective, we have investigated the expression of the CD40, CD80, CD86, PD-1L, B7H2, OX40L and 4-1BBL costimulatory molecules in 10 human NB cell lines, as well as in primary tumour cells isolated from NB patients." (PMID 12771917, 2003). "In parallel, macrophages in tumor-affected lymph nodes showed a shift from MHC class I/IIhi to MHC I/IIlo subsets and reduced co-expression of MHC molecules with CD80 and CD86, indicating impaired antigen-presenting features." (PMID 42158858, 2026). "Indeed, we observed an increased DC activation, as measured by the upregulation of the co‐stimulatory molecule CD86, post immunisation with ACM‐Trp2 + free CpG, aiding the efficient priming of Trp2‐tumour‐specific T cells." (PMID 39873184, 2025). "In the tumor-draining lymph nodes, we observed that adding chemotherapy to innate agonists significantly increased the infiltration of CD86 + mature DCs, but not CD40 + DCs." (PMID 39871312, 2025). "Moreover, following treatment with the combination of SUP3 and Flt3L, CD103 + cDC1s within the tumor continued to exhibit high expression of co-stimulatory molecules, such as CD40, CD80, and CD86 expression." (PMID 41291775, 2025). "Furthermore, tissue immunofluorescence staining underscored the treatment’s efficacy in upregulating the M1 macrophage marker CD86 and downregulating the M2 macrophage marker CD163 within the tumor milieu." (PMID 40664640, 2025). "The expression of CD86 and CD206 as well as M2/M1 index were detected by FCM to identify TAM phenotype, while cytokines related to macrophage activation, including IL-6, TNF-α, and CXCL10, were determined in tumor tissue and serum after treatment." (PMID 39744236, 2025). "Immunofluorescent staining of tumor tissues for the vascular marker CD31 and macrophage markers CD86 (M1) and CD206 (M2) confirmed that Liensinine treatment reduced tumor vascular density, decreased M2 macrophage infiltration, and increased M1 macrophage polarization." (PMID 40665352, 2025). "Expression of CD163, CD209 and CD86 markers was not affected by the presence of tumor cells or by chemotherapeutic treatments, doxorubicin or epirubicin." (PMID 41009763, 2025). "Notably, LBP-CD155L NVs induced a significant increase in the CD86 level and a concomitant decrease in CD206 level within the tumor micro environment (TME)." (PMID 41050703, 2025). "To further investigate the potential correlation between the suppression of tumor growth in BC‐bearing mice induced by H2S and TAM repolarization, we assessed the levels of CD86 and CD206 expression in macrophages isolated from the tumor tissues of BC‐bearing mice." (PMID 39755930, 2025). "Additionally, MYCN-A tumors exhibited the downregulation of immune-activating genes such as CD48 and CD86, and a slight decrease in CD40 expression, potentially contributing to an immunosuppressive tumor microenvironment." (PMID 39860532, 2025). "TZ‐dSA3‐12‐treated E0771‐HER2 cancer cells markedly increased the surface expression of activation markers, including CD40, CD80, CD86, MHC‐I, and MHC‐II on bone marrow‐derived dendritic cells (BMDCs), suggesting that TZ‐dSA3‐12‐treated tumor cells enhance the antigen presentation capacity of DCs." (PMID 40492586, 2025). "Additionally, γδ T cells possess unique advantages, such as the ability to induce immature dendritic cells to express CD86 and MHC class I molecules via TNF-α secretion, MHC-independent antigen recognition, and direct tumor cell lysis." (PMID 41142813, 2025).